ALAS1 (5'-aminolevulinate synthase 1)
Diseases named in the same sentence as ALAS1 in open-access papers (continued):
Sharing a sentence is not in itself a finding about the gene and the disease.
protoporphyria (1 paper, 2021). "The hepatic protoporphyria-inducing drug 4-ethyl-DDC caused induction of hepatic ALAS1 mRNA and protein levels in both WT and +/− mice but markedly less in the mice with only one intact allele." (PMID 34900592, 2021).
schizophrenia (1 paper, 2025). A major psychotic disorder characterized by abnormalities in the perception or expression of reality. "The mechanisms underlying the influence of ALAS1, DNAH1, and PRKCD on schizophrenia are attributed to their proximity to TSS/TES." (PMID 39905509, 2025).
tumor (14 papers, 2009 to 2026). "Furthermore, this also extends to tumor vasculature, as heightened FLVCR1a-ALAS1 axis, linked to increased glycolysis, is a common trait observed in tumor endothelial cells compared to their healthy counterparts." (PMID 38581583, 2024). "The suggested mechanism, indicating that tumor cells utilize the FLVCR1a-ALAS1 axis to restrict oxidative metabolism in favor of aerobic glycolysis, is in strong agreement with the putative role of ALAS1 in glucose regulation proposed above." (PMID 38581583, 2024). "This observed low essentiality of ALAS1 in cancers suggests a potential trafficking route for heme precursors, implying an active tumor microenvironment." (PMID 38649187, 2024). "In conclusion, our work indicates that interfering with the ALAS1-FLVCR1a axis represents a valuable strategy to modulate tumor cell metabolism and improve sensitivity to specific drugs." (PMID 35267538, 2022). "In contrast genes involved in development and differentiation (Arid5b, Inmt, Grem2, Gdap10), cell metabolism (Alas1, Gsta1, Thrsp, Fdft1, Elovl6), tumor growth (SerpinA4, Cish, Rpl36), and cell cycle control (PLK3, Myc, HNF6/Onecut1) were downregulated." (PMID 33004985, 2020). "In addition, another interesting aspect emerged from our findings: our data show that ALAS1 inhibition by ALA has a cytostatic effect on tumor cells, by inhibiting cell proliferation similarly to FLVCR1a-mediated heme export blockage." (PMID 35267538, 2022). "In our study, the expression stability of five reference genes ACTB, ALAS1, GUSB, HMBS, and RPL29 were investigated to determine the CRM1 gene expression profile in tumor tissues and normal tissues by NormFinder analysis." (PMID 38031942, 2023). "Next, we detected the levels of the rate-limiting heme synthetic enzyme ALAS1; heme transport proteins HRG1 and HCP1, which allow heme uptake by tumor cells; and the heme degradation enzyme HO-1." (PMID 29423106, 2018). "Gene expression of Alas1, an enzyme involved in heme biosynthesis, was down-regulated in the TCDD, PCB126 and human HCA profiles but up-regulated in the PCB153 expression profile, suggesting that down-regulation of Alas1 may promote tumor development." (PMID 20959002, 2010). "By integrating bulk and single-cell transcriptomic data, we identify subtype-specific roles of key circadian regulators-including ALAS1, NONO, and CSNK1D-in shaping tumor metabolism, proliferation, stromal remodeling, and immune suppression." (PMID 41898292, 2026).
cancer (11 papers, 2009 to 2024). A tumor composed of atypical neoplastic, often pleomorphic cells that invade other tissues. "The intricate connection between FLVCR1a, ALAS1 and glucose utilization is well exemplified in another pathological condition associated to aberrant FLVCR1a modulation, which is cancer." (PMID 38581583, 2024). "The ensuing discussion on these transport mechanisms has the potential to provide a plausible explanation for the observed low essentiality of ALAS1 in cancer cells, paving the way for our future studies." (PMID 38649187, 2024). "The significantly low gene essentiality of ALAS1 in cancer cells, given its crucial role as an indispensable precursor in heme biosynthesis and its established essentiality for early embryogenesis in the Alas1 KO study, raises intriguing questions." (PMID 38649187, 2024). "We have recently showed that, in SKCO1 and CACO2 cells, as well as in other cancer cell lines, the inhibition of heme export results in a transient accumulation of heme that negatively regulates ALAS1-mediated heme synthesis." (PMID 35267538, 2022). "Recently, we demonstrated the existence of a functional axis between the heme synthetic enzyme ALAS1 and the heme exporter FLVCR1a exploited by cancer cells to down-modulate oxidative metabolism." (PMID 35267538, 2022). "A genome-wide expression study of skeletal muscle biopsies from upper gastro-intestinal cancer patients highlighted ALAS1 as downregulated in patients with cancer cachexia." (PMID 32354332, 2020). "In contrast to ALAS2, the essentiality of ALAS1 is a feature of diverse cancer cells independent of cancer type." (PMID 38649187, 2024).
infection (5 papers, 2014 to 2023). The state of being infected such as from the introduction of a foreign agent such as serum, vaccine, antigenic substance or organism. "Relative expression levels of the control housekeeping gene ALAS1 between the different infections were unaffected during the entire time course experiment." (PMID 30135119, 2018). "We found several reference genes were differentially expressed in infection control mice (i.e., IPO8, PGK1 and ALAS1) in response to sporozoite challenge." (PMID 38030676, 2023). "As expected, the mRNA level of the control housekeeping gene ALAS1 showed no change after infection with any of the lentiviruses used." (PMID 30135119, 2018).
genetic disorder (3 papers, 2020 to 2023). "AHP is an uncommon genetic disorder caused by inborn defects in metabolism, in which the enzyme delta-aminolevulinate synthase 1 (ALAS1), involved in the synthesis of the heme group, is produced in excess." (PMID 36833241, 2023). "ALAS1 is induced in some genetic disorders but unlike other genes in the heme pathway, a gene variant of ALAS1 associated with inherited disease has not been reported." (PMID 34900592, 2021).
ALAS1 also shares sentences with these, for which no sentence is quoted: prostate carcinoma (3 papers); anemia (2); hereditary sideroblastic anemia (2); Impaired glucose tolerance (2); malaria (2); acute kidney injury (1); bipolar disorder (1); blood disease (1); cardiovascular disease (1); cholestasis (1); colorectal neoplasm (1); electrolyte disorders (1); head and neck squamous cell carcinoma (1); Hepatitis (1); hereditary coproporphyria (1); kidney cancer (1); metabolic disorder (1); Obesity (1); oral cancer (1); porphyria cutanea tarda (1); variegate porphyria (1); virus infections (1); X-linked dominant protoporphyria (1); X-linked sideroblastic anemia (1).